TRIP13 (thyroid hormone receptor interactor 13)
Diseases named in the same sentence as TRIP13 in open-access papers (continued):
Sharing a sentence is not in itself a finding about the gene and the disease.
skin cutaneous melanoma (3 papers, 2021 to 2025). "Increased TRIP13 expression was associated with a shorter OS in the following forms of cancer: KIRP, LIHC, ACC, skin cutaneous melanoma (SKCM), mesothelioma (MESO), LUAD, KIRC, and brain lower-grade glioma (LGG)." (PMID 40441196, 2025). "Our results revealed several novel biomarkers and biological pathways that participate in the pathogenesis of cutaneous melanoma, and demonstrated the diagnostic and prognostic value of CDC45, CENPF, DTL, FANCI, GINS2, HJURP, TPX2 and TRIP13." (PMID 33531976, 2021). "However, TRIP13 mRNA expression showed no significant changes in kidney chromophobe (KICH), pheochromocytoma and paraganglioma (PCPG), skin cutaneous melanoma (SKCM), thyroid carcinoma (THCA), and thymoma (THYM)." (PMID 41007830, 2025).
thyroid cancer (3 papers, 2018 to 2025). "Expression levels of TRIP13, TPX2, DLGAP5, KIF2C and TTK were associated with shorter disease free survival (DFS) among differentiated thyroid cancer." (PMID 30386706, 2018). "To date, there is no study focused on the exact role of TRIP13 in the initiation and progression of ATC or other thyroid cancer subtypes." (PMID 30386706, 2018).
acute kidney injury (2 papers, 2017 to 2019). Sudden and sustained deterioration of the kidney function characterized by decreased glomerular filtration rate, increased serum creatinine or oliguria. "TRIP13-deficient tubular epithelial cells tend to progress towards apoptotic cell death following acute kidney injury." (PMID 31739630, 2019). "From these findings, TRIP13 could be a viable therapeutic target to treat acute kidney injury by regulating pathways associated with DNA repair." (PMID 28256593, 2017).
adenoma (2 papers, 2020 to 2022). A neoplasm arising from the epithelium. "TRIP13 expression increased continuously from normal tissue to polyp/adenoma tissue to tumor tissue, suggesting the TRIP13 was related to the tumor progression and upregulated in early premalignant lesions." (PMID 35075117, 2022). "In summary, TRIP13 expression increased continuously from adjacent mucosa to adenoma to early-stage tumor to late-stage tumor, and high expression of TRIP13 conferred a survival disadvantage to CRC patients." (PMID 35075117, 2022). "TRIP13 expression increased continuously from adjacent mucosa to adenoma to early-stage to late-stage tumors." (PMID 35075117, 2022). "The Hub gene, thyroid hormone receptor interactor 13 (TRIP13) whose expression increased continuously from adjacent mucosa to adenoma to early-stage to late-stage tumors was verified in the GSE117606 dataset and tested in the clinical specimens and various CRC cell lines." (PMID 35075117, 2022).
childhood cancer (2 papers, 2018 to 2020). "Typical symptoms of the known MVA syndromes caused by mutations in BUBR1, CEP57, and TRIP13 are intrauterine growth retardation, mental retardation, microcephaly, and childhood cancer, none of which were observed in the patient." (PMID 33094908, 2020). "The observed spontaneous and DMBA-induced cancer phenotypes in Cep57-insufficient mice were unexpected because MVA patients with CEP57 mutations, in contrast to those carrying mutations in BUBR1 and TRIP13, are not known to be predisposed to childhood cancers." (PMID 30035751, 2018).
colorectal adenoma (2 papers, 2022 to 2025). An adenoma that arises from the colon or rectum. "Additionally, TRIP13 is involved in colorectal adenoma-to-carcinoma progression." (PMID 35114976, 2022).
colorectal tumor (2 papers, 2021 to 2022). "In summary, the data presented here illustrate that, for a subset of colorectal tumours exhibiting TRIP13 overexpression, TRIP13 as an attractive therapeutic target." (PMID 35194944, 2022). "In our study, TRIP13 mRNA level increased significantly in both colorectal tumor tissues and peripheral blood compared to the control group." (PMID 33237662, 2021). "In our study, TRIP13 mRNA levels increased significantly in both colorectal tumor tissues and peripheral blood samples compared to controls." (PMID 33237662, 2021). "TRIP13 mRNA level was upregulated in peripheral blood and also significantly upregulated in colorectal tumor tissues (P < 0.05)." (PMID 33237662, 2021).
endometrial carcinoma (2 papers, 2024 to 2025). A malignant tumor arising from the epithelium that lines the cavity of the uterine body. "In endometrial carcinoma, TRIP13 points to a positive connection with immunosuppressive cell infiltration and a negative connection with immune-activating cell infiltration." (PMID 41007830, 2025). "In addition, Kaplan–Meier plotter analysis showed that the overall survival rate and recurrence-free survival rate of endometrial cancer patients with high expression level of TRIP13 were significantly lower than those with low expression level." (PMID 40129972, 2024). "Among these four endometrial cancer cell lines, HEC-1A exhibited relatively high TRIP13 expression, while Ishikawa showed relatively low TRIP13 expression." (PMID 40129972, 2024).
Fanconi anemia (2 papers, 2021 to 2023). Fanconi anemia (FA) is a hereditary DNA repair disorder characterized by progressive pancytopenia with bone marrow failure, variable congenital malformations and predisposition to develop hematological or solid tumors. "The TRIP13 co-expression genes have positive substantial associations in DNA repair machinery like DNA replication, Fanconi anemia pathway, homologous recombination, mismatch repair, nucleotide excision repair, and base excision repair." (PMID 38074464, 2023). "We found that TRIP13 methylation had a negative correlation with related processes, such as DNA replication, mismatch repair, homologous recombination, Fanconi anemia pathway and cell cycle." (PMID 34066132, 2021).
microcephaly (2 papers, 2020 to 2023). A congenital or acquired developmental disorder in which the circumference of the head is smaller than normal for the person's age and sex. "According to GO analysis, these genes are associated with either abnormal hematopoiesis (Aurkb, Fen1, Hrob, Kif20a, Rad51ap1 and Tsr2) or microcephaly (Casc5, Hmgb3, Ncaph and Wdr62), or both (Fanca and Trip13)." (PMID 37661832, 2023).
bile duct cancer (1 paper, 2023). "Furthermore, MYC can induce HMGA1 and TRIP13 transcription by bile duct cancer cells to enhance bile duct cancer cell migration, proliferation, invasion, dryness, and epithelial–mesenchymal transition (EMT)." (PMID 37504265, 2023).
breast invasive carcinoma (1 paper, 2017). "Amplification of TRIP13 was observed in 3.1% of the 974 breast invasive carcinoma samples." (PMID 28968952, 2017).
colitis (1 paper, 2026). Inflammation of the colon. "In addition, we generated Trip13fl/flItgaxcre mice (conditional Trip13 knockout in dendritic cells, DCs) to investigate whether TRIP13 deficiency in DCs affects Treg proliferation and the progression of colitis." (PMID 41535263, 2026). "We also generated cKO mice and found that colitis exacerbation following TRIP13 ablation in Treg cells was obtained after TNBS induction." (PMID 41535263, 2026). "In our study, we demonstrate that TRIP13 overexpression promotes Treg expansion and consequently inhibits the development of colitis in a mouse model induced by T cell transfer." (PMID 41535263, 2026). "In a mouse colitis model, TRIP13 overexpression markedly alleviated colon inflammation by enhancing Treg expansion, an effect that was reversed by HAT1 knockdown." (PMID 41535263, 2026). "Overexpression of TRIP13 promoted Treg expansion, thereby inhibiting the progression of colitis in a mouse T cell transfer model." (PMID 41535263, 2026). "We investigated whether TRIP13 exerts anti-inflammatory effect through Treg expansion in a mouse colitis model induced by transferring naïve CD4+ T cells into lymphopenic Rag1−/− mice (CD45.2+)." (PMID 41535263, 2026). "Collectively, these findings suggest that targeting TRIP13 may represent a promising strategy for preventing colitis by promoting Treg expansion and function." (PMID 41535263, 2026). "Consequently, the control of colitis progression by TRIP13-expressing Tregs is regulated in the inflammatory condition." (PMID 41535263, 2026). "However, the role of TRIP13 in immune cells and its impact on colitis development remain largely unknown." (PMID 41535263, 2026). "Conversely, genetic ablation of TRIP13 substantially reversed the effects induced by HAT1 overexpression, including enhanced Treg expansion and attenuation of colitis." (PMID 41535263, 2026). "Conversely, genetic ablation of TRIP13 substantially reversed the effects induced by HAT1 overexpression, including enhanced Treg expansion and attenuation of colitis, suggesting that TRIP13 is required for HAT1-mediated functions." (PMID 41535263, 2026). "TRIP13 knockout markedly reversed the effects of HAT1 overexpression on Treg expansion and the progression of colitis." (PMID 41535263, 2026). "Mechanistically, TNFR2 signaling elevated TRIP13 expression, which stabilized HAT1 protein by preventing UBE4A-mediated polyubiquitination degradation of HAT1, thus promoting Treg proliferation and protecting against colitis." (PMID 41535263, 2026). "Our results showed that TRIP13 deletion in DCs had no remarkable effect on Treg proliferation or colitis development." (PMID 41535263, 2026).
embryonal tumors (1 paper, 2021). "It has been reported that individuals having biallelic TRIP13 or BUB1B mutations are prone to having embryonal tumors, and their cells display severe spindle assembly checkpoint (SAC) impairment." (PMID 33726794, 2021).
esophageal squamous cell carcinoma (1 paper, 2022). Esophageal squamous cell carcinoma (ESCC) is a type of esophageal carcinoma (EC) that can affect any part of the esophagus, but is usually located in the upper or middle third. "This present study is aimed at investigating the role of high expression of TRIP13 inducing nedaplatin (NDP) resistance in esophageal squamous cell carcinoma (ESCC) cells." (PMID 35601150, 2022).
gallbladder cancer (1 paper, 2024). "Most interestingly three genes TRIP13, NEK2, and TPX2 were identified as key players linked to the development and progression of gallbladder cancer." (PMID 38914609, 2024). "This study, using a network-centric approach, reveals the complex interaction among differentially expressed genes (DEGs) in gallbladder cancer (GBC), highlighting the crucial roles of TRIP13, NEK2, and TPX2 in steering the disease's development and prognosis." (PMID 38914609, 2024).
lentivirus infection (1 paper, 2017). Virus diseases caused by the Lentivirus genus. "The lentivirus infection efficiency is above 85% for both TRIP13-KD lentivirus and Negative Control (NC) lentivirus, so that we can ensure the synchronization of all the following experiments." (PMID 28424416, 2017).
lung squamous cell carcinoma (1 paper, 2025). "The mutation frequency of TRIP13 was the highest in individuals with lung squamous cell carcinoma." (PMID 40441196, 2025).
lymph node metastasis (1 paper, 2022). "We found that high TRIP13 expression was associated with higher malignant phenotype, like more lymph node metastasis (p = 0.002) and distant metastasis (p = 0.024)." (PMID 36268276, 2022). "Additionally, a high TRIP13 level was associated with lymph node metastasis and distant metastasis." (PMID 36268276, 2022).
metastatic tumour (1 paper, 2022). "As TRIP13 has a role in promoting CRC progression, we tested the hypothesis that pharmacologic inhibition of TRIP13 by DCZ0415 inhibits primary and metastatic tumour growth." (PMID 35194944, 2022).
monoclonal gammopathy of undetermined significance (1 paper, 2017). "We firstly compared TRIP13 expression levels in CD138-enriched plasma cells from 22 healthy subjects (normal plasma cells, NPC), 44 subjects with monoclonal gammopathy of undetermined significance (MGUS) and 351 patients with newly diagnosed MM." (PMID 28157697, 2017).
mucinous adenocarcinoma (1 paper, 2020). An invasive adenocarcinoma composed of malignant glandular cells which contain intracytoplasmic mucin. "In mucinous adenocarcinomas, there was high expression of TRIP13, as was the case for all tumor grades." (PMID 33037736, 2020).
mycosis fungoides (1 paper, 2021). Classical mycosis fungoides is the most common type of mycosis fungoides (MF), a form of cutaneous T-cell lymphoma, and is characterized by slow progression from patches to more infiltrated plaques and eventually to tumors. "In human mycosis fungoides tumor, TRIP13 gene expression increased compared to control biopsies." (PMID 33237662, 2021).
neuroblastoma (1 paper, 2025). Neuroblastoma (NB) is the most common solid, extracranial childhood tumor. "However, there is a substantial positive association between the presence of Th1 cells and TRIP13 expression levels in GBM, GBMLGG, BRCA, LUAD, STES, STAD, BLCA, and neuroblastoma (NB) (|correlation coefficient|>0.3, P < .05)." (PMID 40441196, 2025).
pancreatic ductal adenocarcinoma (1 paper, 2025). An infiltrating adenocarcinoma that arises from the epithelial cells of the pancreas. "TRIP13 encodes a thyroid hormone receptor-interacting protein, also known as a hormone-dependent transcription factor, promoting the progression of pancreatic ductal adenocarcinoma by facilitating tumor tissue growth and metastasis." (PMID 41132793, 2025).
plasma cell leukemia (1 paper, 2023). An aggressive plasma cell neoplasm characterized by the presence of neoplastic plasma cells in the peripheral blood. "Additionally, the overexpression of YWHAE and TRIP13 was determined to be associated with an advanced tumor stage, and patients with plasma cell leukemia (PCL) had higher YWHAE levels." (PMID 38012658, 2023).
squamous cell carcinoma (1 paper, 2017). A carcinoma arising from squamous epithelial cells. "Overexpression of TRIP13 has been shown to result in malignant transformation of non-malignant cells and high expression of TRIP13 in squamous cell carcinoma of the head and neck can lead to aggressive, treatment-resistant tumors and enhanced repair of DNA damage." (PMID 28056099, 2017).
T-cell leukemia (1 paper, 2024). A malignant disease of the T-lymphocytes in the bone marrow, thymus, and/or blood. "We next asked whether TRIP13 knockdown can affect the proliferation of T-cell leukemia JURKAT cells." (PMID 38464090, 2024).
viral infection (1 paper, 2021). "The function of TRIP13 does not lend itself to being an obvious benefit or hinderance to viral infection, as would be considered by a protein with known host innate viral immunity activity." (PMID 33208020, 2021).
tumor (78 papers, 2008 to 2026). "We have systematically discussed the association between the TRIP13 expression level and clinical prognosis, tumor microenvironment (TME), DNA methylation, tumor mutational burden (TMB), microsatellite instability (MSI), and drug sensitivity in 33 cancers." (PMID 40441196, 2025). "Subsequently, we explored the relationship between TRIP13 expression-associated alterations and clinical prognosis, DNA methylation, immune cell infiltration, immune checkpoints, tumor mutational burden, microsatellite instability, and drug sensitivity." (PMID 40441196, 2025). "Next, the relationship between immune-associated genes and differential TRIP13 expression was investigated in 33 distinct tumor types." (PMID 40441196, 2025). "TRIP13 is identified as a tumor associated protein in various tumors but its function in oncogenesis is still not clear." (PMID 38074464, 2023). "Plin2 expression in different tumor cells confers susceptibility to cell death induced by Trip13 depletion as well as treatment with paclitaxel, a spindle‐interfering drug commonly used against different cancers." (PMID 36031387, 2022). "A significant association was observed between the mRNA expression of TRIP13 with the CRC tumor grade." (PMID 35075117, 2022). "Specifically, perilipin 2 confers susceptibility to Trip13‐knockdown‐ and antimitotic‐drug‐induced cell death, allowing for stratification for paclitaxel‐treatment‐responsive tumor cells." (PMID 36031387, 2022). "Similarly, our GC cohort showed upregulated TRIP13 protein expression in GC tissues, linked to tumor depth." (PMID 41007830, 2025). "Furthermore, overexpression of TRIP13 was associated with tumor metastasis through activation epithelial-mesenchymal transformation pathways." (PMID 37627217, 2023). "Collectively, our analysis implied that TRIP13 may play a potential role in tumor maintenance linked to GBM recurrence." (PMID 34066132, 2021). "Finally, the subcutaneous tumour formation experiment in mice confirmed that overexpression of DDX21 after knocking down TRIP13 could partially restore the inhibition of subcutaneous tumours in mice caused by knocking down TRIP13." (PMID 39187490, 2024). "TRIP13 primarily activates pathways such as ubiquitination, cell cycle regulation, and DNA repair to drive tumor progression." (PMID 42099656, 2026). "TRIP13 inhibitors have shown the potential to enhance cytotoxicity and promote tumor regression when combined with immune checkpoint inhibitors that target PD-1 and CTLA-4." (PMID 41535263, 2026). "Depletion of TRIP13 enhances immune activation within the tumor microenvironment, ultimately slowing tumor progression." (PMID 41535263, 2026). "Correspondingly, tumor-associated target genes including ALDH3A2, SEMA3F, MAP4K5, and TRIP13 were upregulated, whereas PIK3IP1, AGO2, MMP2, and RALBP1 were suppressed." (PMID 41897301, 2026). "Previous studies have identified the crucial role of TRIP13 in tumor immunity, where it supports tumor survival by modulating the recruitment of immune cells, including CD3+, CD4+, and CD8+ T cells, into the tumor microenvironment." (PMID 41535263, 2026). "TRIP13 has a recognized part in driving tumor progression across different cancer types, yet its precise role in GC remains beyond our full comprehension." (PMID 41007830, 2025). "Functional experiments confirmed that TRIP13 contributes to ccRCC malignancy by enhancing tumor proliferation (via Ki67 and PCNA), promoting migration and invasion, and facilitating immune escape." (PMID 41487520, 2025). "In vivo xenograft assays further validated that TRIP13 knockdown markedly suppresses tumor growth, emphasizing its role as a multifaceted oncogenic driver." (PMID 41487520, 2025). "Although these findings demonstrate TRIP13’s tumor-promoting effects, its mechanistic relationship with mitophagy remains largely unclear." (PMID 41487520, 2025).